ANKFN1 (ankyrin repeat and fibronectin type III domain containing 1)
Description:
May play a role in neuronal function.
Synonyms: FLJ38335; WAKE
Tractability: Antibody: the Human Protein Atlas places it where antibodies can reach. PROTAC: ubiquitination databases record sites on it.
Gene: Protein-coding gene on chromosome 17 (55,882,301 to 56,517,016, forward strand). Ensembl gene ENSG00000153930.
Subcellular location (Human Protein Atlas): Nucleoplasm; Plasma membrane
Gene Ontology:
Biological process: establishment of mitotic spindle orientation; regulation of establishment of bipolar cell polarity
Cellular component: spindle
Genetic constraint (gnomAD): Loss-of-function variants: 59 observed, 98.94 expected, observed/expected ratio (o/e) 0.6, 90% interval 0.48 to 0.74. The upper end of that interval is the gene's LOEUF score, 0.74, which puts it in group 3 of 6, group 1 being the genes least tolerant of losing a copy. Missense variants: 1,414 observed, 1,375.9 expected, observed/expected ratio (o/e) 1.03, 90% interval 0.98 to 1.07. Synonymous variants: 518 observed, 519.62 expected, observed/expected ratio (o/e) 1, 90% interval 0.93 to 1.07.
Homologues: Orthologues: chimpanzee ANKFN1 (99% identical), macaque ANKFN1 (97% identical), dog ANKFN1 (90% identical), pig ANKFN1 (90% identical), rabbit ANKFN1 (90% identical), mouse Ankfn1 (90% identical), tropical clawed frog ankfn1 (68% identical), guinea pig ANKFN1 (62% identical), zebrafish ankfn1a (60% identical).
Diseases named in the same sentence as ANKFN1 in open-access papers:
ANKFN1 is named in the same sentence as 13 diseases in open-access papers, as found by Europe PMC text mining. Sharing a sentence is not in itself a finding about the gene and the disease. The quoted sentences say what the papers report.
hepatocellular carcinoma (3 papers, 2022 to 2024). A malignant tumor that arises from hepatocytes. "Besides its roles in vestibular-related functions, ANKFN1 plays pro-tumorigenic and metastatic roles in hepatocellular carcinoma." (PMID 39766302, 2024). "Ankyrin repeat and fibronectin type III domain containing 1 (ANKFN1) is reported to be involved in human height and developmental abnormalities, but the expression profile and molecular function of ANKFN1 in hepatocellular carcinoma (HCC) remain unknown." (PMID 35725908, 2022).
cannabis dependence (2 papers, 2021 to 2024). Physical and psychological dependence on the drug cannabis. "Little is known about Ankfn1 but it has been genetically linked to cannabis dependence." (PMID 38217668, 2024).
bladder cancer (1 paper, 2024). "Ankfn1, Gstt2, Plec, Gphn, Fmo5, Cmss1, Ahnak, Mecom, Slc2a1, Gsta4, Kras, Peak1, and Hmga2 were associated with worse disease-free survival in bladder cancer patients." (PMID 39769061, 2024). "An 11-gene signature (Hmga2, Peak 1, Kras, Slc2a1, Ankfn1, Ahnak, Cmss1, Fmo5, Gphn, Plec, Gstt2) had the most substantial impact on disease-free survival in bladder cancer patients." (PMID 39769061, 2024).
Cirrhosis (1 paper, 2022). A chronic disorder of the liver in which liver tissue becomes scarred and is partially replaced by regenerative nodules and fibrotic tissue resulting in loss of liver function. "The upregulation of ANKFN1 in HCC was associated with cirrhosis, alpha-fetoprotein (AFP) levels and poor prognosis." (PMID 35725908, 2022). "The results showed that ANKFN1 expression was positively associated with cirrhosis (P = 0.005) and serum alpha-fetoprotein (AFP) levels (P = 0.045)." (PMID 35725908, 2022). "Multivariate Cox proportional hazard analysis showed that the combination of ANKFN1 protein levels (P = 0.016) and cirrhosis (P = 0.023) was an independent prognostic factor for worse OS in patients with HCC." (PMID 35725908, 2022). "Further multivariate Cox regression analysis showed that the ANKFN1 protein level, together with cirrhosis, was an independent prognostic factor for OS in patients with HCC." (PMID 35725908, 2022). "Furthermore, the univariate Cox proportional hazard analysis results revealed that Edmondson’s grade (high‐medium vs. low; P = 0.039), cirrhosis (P = 0.002), and ANKFN1 protein level (low vs. high; P = 0.046) were indicators of worse survival in HCC patients." (PMID 35725908, 2022). "Next, through analysis of the ANKFN1 IHC scores in HCC tissues, we observed that high HCC expression correlated with cirrhosis and higher AFP levels." (PMID 35725908, 2022).
liver cancer (1 paper, 2022). An epithelial or non-epithelial malignant neoplasm that arises from the liver. "We detected multiple genomic HBV integrations in two distinct types of liver cancer, with recurrent events at TERT, ZMAT4, MET, ANKFN1, PLXNB2 in ICC, and TERT, ALKBH5 in CHC." (PMID 36123506, 2022).
cancer (2 papers, 2020 to 2022). A tumor composed of atypical neoplastic, often pleomorphic cells that invade other tissues. "Overall, ANKFN1 is a potential precision cancer treatment target." (PMID 35725908, 2022). "To further clarify the role of ANKFN1 in HCC migration and invasion in vitro, we postulated that ANKFN1 promotes cancer migration and invasion by regulating the RhoA/JNK signaling pathway." (PMID 35725908, 2022). "Studies have shown that the last 50 amino acids of PTEN, which match the intronic region between exons 3 and 4 of ANKFN1, are related to human height, but their involvement in cancer has never been reported." (PMID 35725908, 2022).
tumor (2 papers, 2022). "The results of xenograft HCC tumor experiments in nude mice showed that the overexpression of ANKFN1 promoted HCC cell migration and invasion." (PMID 35725908, 2022). "Consistently, the downregulation of ANKFN1 sharply reduced the tumor volume and nude mouse weight." (PMID 35725908, 2022). "Similar to the in vitro results, compared with the control conditions, the overexpression of ANKFN1 promoted HCC growth, as indicated by changes in tumor volume." (PMID 35725908, 2022). "Here, we showed that ANKFN1 was upregulated in 126 tumor tissues compared with adjacent nontumorous tissues in HCC patients." (PMID 35725908, 2022).
ANKFN1 also shares sentences with these, for which no sentence is quoted: atypical hemolytic-uremic syndrome (1 paper); dementia (1); microangiopathic hemolytic anemia (1); nicotine dependence (1); renal failure (1); Thrombocytopenia (1).